OLIG2 (oligodendrocyte transcription factor 2)
Diseases named in the same sentence as OLIG2 in open-access papers (continued):
Sharing a sentence is not in itself a finding about the gene and the disease.
tumor (continued). "All tumours showed cells with enlarged, pleomorphic and occasional hyperchromatic nuclei on H&E, whilst all conditions show diffuse staining for GFAP (cytoplasmic) and SOX2 (nuclear), with a smaller fraction positive for OLIG2." (PMID 31988455, 2020). "In future studies, it might be interesting to analyse the expression of OLIG2 and CCND2 also at the invasive tumor edge and to perform validation of our biomarkers with different techniques such as RNA sequencing." (PMID 31568682, 2020). "Colocalization analysis revealed that 48% of ASCL1+ tumor cells were positive for the proliferation marker Ki67, whereas over 90% of ASCL1+ cells were OLIG2+ and SOX2+, indicating that these three transcription factors are coexpressed in the majority of the PDX‐GBM cells in vivo." (PMID 32573857, 2020). "OLIG2 expression was positive (> 50% of tumours cells) in 7 cases, intermediate (10–50% of tumour cells) in 1 case and negative (< 10% of tumour cells) in 37 cases." (PMID 31493794, 2019). "Cells positive for Nestin, CD133, GFAP, BIIIT, SSEA4, and Olig2 had a tumor-dependent pattern of expression, which did not have a dichotomous association with grade." (PMID 29849507, 2018). "Recently, the transcriptional network ZEB1/OLIG2/SOX2 has been shown to be crucial in GBM irrespective of driver mutations, playing an important role in tumor initiation, stemness properties, proliferation and tumorigenicity." (PMID 30158599, 2018). "The tumor was positive for OLIG2 and GFAP and negative for BRAF V600E and IDH1 R132H mutant protein immunostains." (PMID 29141672, 2017). "By contrast, tumors derived from CD44+ expressing PDGCs MU028 and MU039 generated a mixture of tumor cells with discrete cells expressing Olig2+, CD44+ or neither marker." (PMID 28241049, 2017). "OLIG2 expression is present in the nuclei of IGCs, while no expression was detected in the tumor core." (PMID 25365423, 2014). "There was no expression of oligodendrocyte transcriptor-2 (Olig-2), epidermal growth factor receptor (EGFR), neurofilament (NF), CD117, nestin or microtubule-associated protein 2 (MAP2) in the tumor cells." (PMID 24348765, 2014). "Using this analysis, most of the genes identified as specific to GBM TAAs when compared to low grade (WHO Grade II) TAAs were also identified as arising only in the stromal compartment of the tumor and not in the Olig2-expressing tumor cells." (PMID 22393407, 2012). "This analysis enables us to identify genes specific to stromal cells, as these genes would only be expressed in the whole tumor population and not in the purified Olig2+ tumor cell population." (PMID 22393407, 2012). "Analysis of tumors generated in Olig2-rpGFP mice infected with RCAS-PDGF-RFP showed that most of the PDGF-RFP infected cells were Olig2-expressing cells, consistent with the idea of an oligodendrocyte lineage in tumor cells derived by PDGF over-expression." (PMID 22393407, 2012). "Taken together, these data confirm that genes expressed in GBM TAAs are expressed predominately in the stromal microenvironment rather than in the Olig2-expressing tumor cells." (PMID 22393407, 2012). "Despite the proliferation-promoting effect of Olig2 gene, we did not observe a gross tumor formation." (PMID 19772605, 2009). "They displayed low levels of Ki67, Olig2, and DCX and higher levels of the mature neuronal marker NeuN, suggesting that overexpression of Foxr2 alone may lead to lesions that harbor differentiated cells and fewer proliferative or stem-like tumor cells." (PMID 39495206, 2025). "The excised tumor tissue was sent to a board-certified pathologist for histopathological analysis and additional immunohistochemistry (IHC) testing, including markers for cytokeratin AE1/AE3, vimentin, oligodendrocyte transcription factor 2 (Olig2), and glial fibrillary acidic protein (GFAP)." (PMID 40362055, 2025).
tumor (continued). "Recent studies have revealed that OLIG2 and ASCL1 bind to each other’s genomic loci and downstream targets, cooperatively regulating tumor cell plasticity and heterogeneity, suggesting that transcription factor gene combinations—rather than individual factors—may drive tumor progression." (PMID 40428395, 2025). "Additional studies demonstrated that Olig2 deletion reduces tumor growth and drives a phenotypic shift from oligodendroglial to astrocytic features, concomitant with PDGFRA downregulation and compensatory EGFR signaling pathway activation, revealing alternative routes for tumor recurrence." (PMID 40428395, 2025). "Taken together, our findings imply that ASCL1 and OLIG2 function redundantly downstream of TNP-deletion to transform affected radial glia into proliferating tumor cells, but these transcription factors seem to regulate opposing aspects of tumor cell migration in the brain." (PMID 39609428, 2024). "Notably, ASCL1 and OLIG2 sit at the apex of the GBM cellular hierarchy, where their dynamic co-expression and functional interactions are directly responsible for determining NSC/astrocyte-like and OPC-like tumor cells, respectively." (PMID 39609428, 2024). "Interestingly, neither Ascl1-CKO nor Olig2-CKO had a significant impact on tumor cell proliferation at P30 or terminal stages." (PMID 39609428, 2024). "Tumor cells are GFAP-positive but negative for OLIG2 and neuronal markers." (PMID 38544524, 2024). "We hypothesized that if ASCL1 is required to promote tumor migration, then increasing the levels of ASCL1 should overcome the repression by OLIG2, resulting in a highly migratory and diffuse tumor phenotype similar to Olig2-CKO tumors." (PMID 39609428, 2024). "Olig2 and synaptophysin IHC were positive in the tumor cells while GFAP was mostly negative." (PMID 39409964, 2024). "In the present study, we explored the expression profile and mode of action of CELF2 in our collection of GBM tissue samples representative of mitotic tumor territories enriched in OLIG2-positive cells or, conversely, non-mitotic tumor areas poor in OLIG2-positive cells." (PMID 37894405, 2023). "Interestingly, this tumor met two of the three essential DMG diagnostic criteria (midline location and infiltrative, but did not express Olig2)." (PMID 36104744, 2022). "The tumor cells were also negative for oligodendrocyte transcription factor 2 (OLIG2)." (PMID 36414742, 2022). "MES tumours express mesenchymal markers such as chitinin-3-like protein (CHI3L/YKL40) and vimentin, and they downregulate proneural markers such as oligodendrocyte transcription factor 2 (Olig2), thus showing an upregulation of angiogenesis and proliferation-related genes." (PMID 35008787, 2021). "Tumor cells strongly expressed OLIG2 and to a lesser extent synaptophysin but not GFAP nor CD34." (PMID 32605662, 2020). "Furthermore, OLIG2 expression is present in the tumor cells and described to be absent in ependymal tumors." (PMID 32103286, 2020). "The tumor strongly expressed OLIG2 and synaptophysin but not neurofilament nor chromogranin A." (PMID 32605662, 2020). "Tumor cells were positive for Olig2, PS100 and ATRX, and negative for R132H-IDH1." (PMID 30857565, 2019). "Tumour tissues were analyzed from metastases in both cases, but this may not explain OLIG2 negativity since more metastatic versus primary site cases should be investigated." (PMID 31493794, 2019). "We used fluorescence immunohistochemistry (F-IHC) to examine expression of OLIG2, a progenitor marker that was expressed in a majority of PA cancer cells based on scRNA-seq, and of GFAP, a top marker of the AC-like gene programme, in the context of the PA tumor architecture." (PMID 31427603, 2019). "In addition, we selected OLIG2 (top 7th gene) as a well known immunohistochemical marker for other tumours but not investigated in RMS." (PMID 31493794, 2019).
tumor (continued). "In addition, immunohistochemistry showed widespread Olig2 staining in tumor cells but not in the cortex of IDH1R132H–PDGFB mice." (PMID 30416682, 2018). "These GHB repressive effects are consistent with suppression of GBM cell tumorigenic properties upon SSADH downregulation as well as finding elevated GHB/α-KG ratios with scarce SSADH expression in tumor territories characterized by low numbers of proliferating cells and lack of Olig2 expression." (PMID 28032215, 2017). "While we cannot exclude that a tumour might arise from the few proliferative cells that persist to later ages, proliferation data favour an origin for DIPG during the single, early-childhood proliferative peak, from Sox2+Olig2+ progenitors." (PMID 27188978, 2016). "Our results indicate that TFAP2B, ALK and a novel marker OLIG2 may serve as surrogate markers for PAX3/7-FOXO1 status what is especially beneficial in cases where poor quality tumour tissue is not suitable for reliable genetic analyses or shows inconclusive result." (PMID 31493794, 2019). "Conversely, GFP+ cells in Olig1/2F/F; H2bF/+ mice showed no co-labeling with OLIG2 or SOX10, confirming that the deletion of Olig1/2 in tumor cells did not alter the astrocytic GBM cell phenotype." (PMID 40428395, 2025). "The immunophenotype of the tumor did not reveal a clear line of origin, with negative staining for GFAP, OLIG2, S100 protein, SOX10, desmin, pankeratin, synaptophysin, and only focally positive vimentin." (PMID 40159593, 2025). "Using immunohistochemistry, all tumors except one (case #14 which presented a GFAP staining in a part of the tumor) expressed GFAP diffusely, and presented no or only focal immunopositivity for Olig2 and SOX10." (PMID 38581034, 2024). "The median survival of Ascl1-OE tumor mice (72 days), though not different from control, was significantly shorter (p < 0.0001) compared to Ascl1-CKO and Olig2-CKO tumor mice." (PMID 39609428, 2024). "Immunohistochemically, tumor cells reveal positivity for GFAP only, while they are negative for MAP2, OLIG2, and CD34." (PMID 38544524, 2024). "Thus, unlike ASCL1, this suggests that OLIG2 may function as a suppressor of tumor cell migration." (PMID 39609428, 2024). "Using immunohistochemistry, tumor cells diffusely expressed GFAP and showed no or only focal expression of Olig2 and SOX10." (PMID 38581034, 2024). "In contrast, dCKO showed no incorporation of EdU within tdTOM+ cells at P30 or even in the few terminal-stage dCKO tumors, indicating that tumor cell proliferation was significantly compromised in the absence of both ASCL1 and OLIG2." (PMID 39609428, 2024). "Immunostaining of TK-EPN862 tumor cells was consistent with the features of EPN, including negative staining for OLIG2 and synaptophysin, positive staining for GFAP, and intracytoplasmic dot-like positivity for EMA." (PMID 36937401, 2023). "Here, we show that the RNA binding protein CELF2 is strongly expressed in mitotic and OLIG2-positive GBM cells, while it is downregulated in differentiated and non-mitotic cells by miR-199a-3p, exemplifying GBM intra-tumor heterogeneity." (PMID 37894405, 2023). "By immunohistochemistry, the tumour strongly expressed S100 and GFAP in addition to intense nestin positivity, while OLIG2 was negative in the perivascular tumour cells." (PMID 37362245, 2023). "Immunostaining for markers of glial differentiation (GFAP and OLIG2) was mostly negative, with only a few PLAGL2-amplified tumors showing labeling of rare scattered tumor cells." (PMID 36437415, 2023).
tumor (continued). "In contrast, positive OLIG2 and GFAP staining (> 5% of tumor cells) was present in many SHH-1A and SHH-1B, but absent in SHH-2." (PMID 35501487, 2022). "As for the makers such as GFAP, Olig-2, and NSE, the negative findings indicated that different recurrence patterns do not result from the cell types from which the tumor origins." (PMID 33585189, 2020). "PDGFRα was also highly coexpressed by the ASCL1+ and OLIG2+ (not shown) tumor cells, whereas GFAP and to a lesser extent S100β and NEUN, although found in some parts of the tumor, did not overlap significantly with SOX2 or ASCL1." (PMID 32573857, 2020). "IHC/immunofluorescence analysis of CD24+ and CD24- cell-initiating tumours identified diffuse CD24 expression throughout both tumour populations that did not co-label with GFAP or Olig2+." (PMID 30657775, 2019). "Bcan-Ntrk1-induced tumors showed elevated percentage of Ki67-positive cells, were positive for OLIG2 and NESTIN, negative for the neuronal marker NeuN and GFAP-positive cells were almost exclusively detected at the normal/tumor border." (PMID 29654229, 2018). "The tumor demonstrated extensive immunostaining with GFAP and OLIG2 (not shown), and was negative for BRAF V600E and for IDH1 R132H mutant protein." (PMID 29141672, 2017). "The oligodendrocyte precursor marker OLIG2, which is common to all DIPG, was robustly detected in most if not all tumor cells in primary human and mouse xenograft DIPG samples." (PMID 28881750, 2017). "Immunohistochemically, the tumor cells were positive for S-100 protein, glial fibrillary acidic protein (GFAP), and epithelial membrane antigen (EMA) with dot-like positivity, and negative for oligodendrocyte transcription factor 2 (Olig2)." (PMID 40896082, 2025). "To investigate if the reduction in tumor cells without Olig1/2 resulted from the altered microenvironment, we investigated the correlation between the expression levels of OLIG1 and OLIG2 and the abundance of six tumor-infiltrating immune cell types in GBM by TIMER." (PMID 40428395, 2025). "The tumor cells typically test positive for GFAP and negative for Olig2." (PMID 38137148, 2023). "Most notably, the tumor was found to be negative for Brachyury, CD68, SRY-box transcription factor 10 (SOX10), HMB45, glial fibrillary acidic protein, oligodendrocyte transcription factor 2, anaplastic lymphoma kinase, desmin, CD117, synaptophysin, and neurofilament." (PMID 37598295, 2023). "On univariate analyses, longer overall survival was also associated with older age (> 3 years) and positive ASCL1 staining, but not OLIG2 or GFAP staining, tumor location, gross total resection or the presence of pathogenic/likely pathogenic SMARCB1 germline variants." (PMID 35501487, 2022). "Higher Olig2 and GFAP/MCM2 densities in FCD3b may reflect margins of the tumour infiltration zone rather than true cortical dysplasia." (PMID 33370704, 2021). "Neither of the tumor cell markers glial fibrillary acidic protein (GFAP) and Olig2 was detected." (PMID 31329636, 2019). "By monitoring the changes in cellular phenotype using CD133/Olig2 and CD44 markers in the clinic, an improved therapeutic regimen could be designed to minimize acquisition of non-genetic tumor resistance." (PMID 28241049, 2017). "Furthermore, when TRAF4 was knocked out, OA could no longer inhibit the expression of SOX2, Olig2, and MMP9, nor did it impair tumor sphere formation." (PMID 39716976, 2025). "By immunohistochemistry, the tumor cells expressed synaptophysin, chromogranin, NKX2.2 (diffuse, nuclear), GFAP (patchy), SMI31 (neurofilament) (focal, cytoplasmic), and TdT (diffuse, nuclear), while lacking expression of CD99, TTF-1, CK 20, MCPyV, PHOX2B, Olig2, OCT3/4, CD45, CD3 and PAX5." (PMID 38031161, 2023).
tumor (continued). "In addition, the tumor cells may be positive for nuclear NeuN but negative for cytoplasmic IDH1- R132H, epithelial membrane antigen (EMA), cytokeratin (CK), and nuclear Olig-2." (PMID 33964714, 2021). "The astrocytic component of OAC may represent a focal area of Id4 expression in tumor subpopulations occurring at later stages after tumor initiation, leading to the co-expression of Id4 with OLIG1 and OLIG2 in neoplastic astrocytes and lack of Id4 expression in neoplastic oligodendrocytes." (PMID 16018821, 2005).